IRS1 (insulin receptor substrate 1)
Diseases named in the same sentence as IRS1 in open-access papers (continued):
Sharing a sentence is not in itself a finding about the gene and the disease.
Insulin resistance (continued). "IRS1 has been flagged as a risk locus for insulin resistance and type II diabetes, and also several cancers." (PMID 36324510, 2022). "Another in vivo study showed that 12 weeks of PM2.5 exposure activated the c-Jun n-terminal kinase signaling pathway, increased insulin receptor substrate-1 phosphorylation, and caused significant liver damage with hepatic insulin resistance." (PMID 36011940, 2022). "It has been indicated that the rs2943641 C allele was associated with increased insulin resistance and hyperinsulinaemia, as well as reduced levels of IRS1 protein." (PMID 36009479, 2022). "IRS-1 causes insulin resistance, while IRS-2 is needed for hepatic insulin activity, and its increase is related to prediabetes." (PMID 36290594, 2022). "The activation of IRS-1/Akt signal pathway caused enhanced insulin action and then improved insulin resistance in rats fed with a high fat diet as shown in our study." (PMID 35487948, 2022). "For example, ER stress has been shown to be associated with insulin resistance, which was accompanied by a suppression of insulin receptor signaling and serine phosphorylation of insulin receptor substrate-1 (IRS-1), in vivo and in vitro." (PMID 35615361, 2022). "In endothelial cells, miR-155 was repressed by insulin and insulin resistance due to impaired signaling by a variant of IRS1 (Arg972 IRS1) resulting in an upregulation of miR-155." (PMID 35955975, 2022). "A well-recognized mechanism of obesity-related insulin resistance is associated with the functional deficiency of IRS-1 phosphorylation, which results in abnormal insulin action." (PMID 35326098, 2022). "Although serine phosphorylations of IRS-1 constitute a well-established mechanism for insulin resistance, several studies have demonstrated that reductions in IRS-1 protein levels are also a significant risk factor for insulin resistance and T2DM." (PMID 35328400, 2022). "At the molecular level, insulin resistance is often associated with impaired tyrosine phosphorylation of IRS-1 despite normal activation of the insulin receptor." (PMID 35625574, 2022). "Impaired insulin responsiveness/insulin resistance is commonly linked to serine phosphorylation of IRS-1; phosphorylation of IRS-1 on Ser307 (human Ser312) results in its dissociation from the insulin receptor, and also impairs insulin downstream signaling." (PMID 35739993, 2022). "Brain insulin resistance is considered an early and common feature of AD, which seems to be closely associated with the IRS-1 dysfunction." (PMID 35563135, 2022). "For example,Tumor necrosis alpha (TNF-α) directly causes insulin resistance through insulin receptor substrate-1 (IRS-1) and insulin receptor substrate-2 (IRS-2 via promoting serine/threonine phosphorylation of the substrates." (PMID 35401518, 2022). "Activated JNK induces Ser 307 phosphorylation of insulin receptor substrate-1 (IRS-1), which alters insulin downstream signaling, and subsequently causes systemic insulin resistance, metabolic syndrome, and T2D." (PMID 34769060, 2021). "Another study reported that the effect of IRS1 polymorphism on hepatic insulin resistance and he showed decreased hepatic levels, reflecting reduced insulin signaling activity." (PMID 34449768, 2021). "The activation of NF-κB causes the production of inflammatory cytokines that promote insulin resistance whilst activating MAPK to reduce insulin receptor substrate-1 (IRS-1) serine phosphorylation, thereby causing insulin resistance." (PMID 33435215, 2021). "Some of them reported that insulin resistance and obesity are closely associated with enhanced IRS-1 expression, and some of them demonstrated opposite results." (PMID 34956089, 2021). "Further, IRS1 polymorphism is a significant genetic determinant for insulin resistance in OSA and NAFLD." (PMID 34449768, 2021).
Insulin resistance (continued). "Here, we examined the association of human brain insulin resistance, as assessed by molecular signaling measures including IRS1 and serine/threonine-protein kinase [AKT], with pathologically-defined cerebrovascular disease." (PMID 33858515, 2021). "JNK, one of the most investigated signal transducers in obesity and insulin resistance, was reported to promote insulin resistance via association with IRS1." (PMID 33510836, 2021). "Hyperinsulemia and insulin resistance are implicated in cancer cell proliferation and survival by activation of IRS-1 and RAS/MEK/ERK pathways." (PMID 39087082, 2021). "Macrophage infiltration into adipose tissue releases TNF-α resulting in serine phosphorylation of insulin receptor substrate 1 (IRS-1) which causes insulin resistance through impaired insulin signaling." (PMID 34790202, 2021). "Phosphorylation of IRS-1 at Ser307, a potential mechanism underlying insulin resistance, attenuates insulin signaling pathways." (PMID 33968046, 2021). "It has been reported that SOCS-1 and SOCS3 are associated with insulin resistance in various cells through degradation of IRS-1 and IRS-2." (PMID 34416903, 2021). "It was postulated that, elevated IL-6 level is associated with insulin resistance and the development of types 2 diabetes mellitus through its suppressive effect on glucose transporter-4 and insulin receptor substrate-1 expression." (PMID 33905632, 2021). "Insulin resistance in adipocytes is associated with impaired phosphorylation of insulin receptor substrate 1 (IRS-1) in obesity, which is further impaired in T2DM." (PMID 34630157, 2021). "A previous study has reported that brain insulin resistance leads to memory loss and inhibits the IRS-1/phosphoinositide 3-kinase/AKT/GSK-3β pathways." (PMID 33859286, 2021). "Downstream of receptor activation is JNK, which, when activated, can cause increased Ser/Thr phosphorylation of IRS1/2, reducing their Tyr phosphorylation by the activated insulin receptor and thus causing insulin resistance." (PMID 32183037, 2020). "Angiotensin II can cause insulin resistance by interfering with the insulin-stimulated increase in insulin receptor substrate 1-associated PI3K activity." (PMID 33240326, 2020). "Mice deficient in IRS1 by targeted disruption display insulin resistance and impaired glucose tolerance and mice heterozygous for defects in genes for both IRS1 and the insulin receptor or IRS1 and glucokinase develop overt diabetes." (PMID 32411229, 2020). "The mTOR/receptor complex is activated by Akt and phosphorylase S6 Kinase, which has been reported to cause insulin resistance by serine phosphorylation of insulin receptor substrate-1 (IRS-1), eventually disrupting PI3K-Akt signaling." (PMID 32294959, 2020). "IRS1 and p85α/p110β ratio was associated with the evolution of insulin resistance after bariatric surgery." (PMID 31936857, 2020). "Phosphorylation of Irs1 prevents its association with the insulin receptor and thus can inhibit insulin action and result in insulin resistance." (PMID 33330474, 2020). "Neu3 sialidase activity induced by olanzapine, an antipsychotic agent associated with insulin resistance, attenuated insulin-induced phosphorylation of insulin growth factor receptor and IRS1, contributing to insulin resistance." (PMID 32251344, 2020). "The improvement of body mass index (BMI) and HOMA-IR (homeostasis model assessment of insulin resistance index) after bariatric surgery was associated with a higher IRS1 and a lower p85α/p110β ratio." (PMID 31936857, 2020). "In our study we showed that treatment of NAFLD mice with the TNFR1 antibody indeed leads to a significant improvement of insulin resistance which was associated with a decreased Ser307 phosphorylation of IRS1 in the liver." (PMID 32235829, 2020).
Insulin resistance (continued). "JNK activation in the liver, muscle and adipose tissue of obese ob/ob mice is linked with insulin resistance and phosphorylation of serine 307 of IRS1, while deletion of JNK1 protected these mice from insulin resistance." (PMID 33303821, 2020). "Appealingly, it was also proposed that the TNF-α role in insulin resistance development is associated with increased serine phosphorylation of IRS1 and decreased expression of GLUT4." (PMID 32932777, 2020). "Neutrophils release TNF-α and IL-6 which cause insulin resistance directly via serine phosphorylation of IRS-1." (PMID 33208757, 2020). "Disruption of the insulin-receptor substrate 1 gene caused insulin-resistance with defects in insulin signaling and led to an extension of lifespan by 14–16%." (PMID 32819363, 2020). "ER stress upregulates glycogen synthase kinase 3 (GSK3), which causes insulin resistance by phosphorylating insulin receptor substrate 1 (IRS1), which subsequently undergoes ubiquitination and proteosomal degradation." (PMID 32774668, 2020). "At a placental level, adiponectin causes insulin resistance by activating PPARα and inhibiting insulin receptor substrate 1 phosphorylation, which reduces insulin responsiveness." (PMID 33029393, 2020). "Many loci associated with adiponectin levels are shared with other insulin resistance traits and risk of type 2 diabetes, including loci near IRS1, LYPAL1, ARL15/FST, VEGFA, CMIP, and PEPD." (PMID 32915782, 2020). "IRS1 is an important regulator of insulin signaling and the loss of IRS1 leads to insulin resistance." (PMID 33197889, 2020). "Activated LPS/TLR4 signaling in Kupffer cell causes insulin resistance through inhibition of insulin receptor substrate-1 phosphorylation in the liver." (PMID 32149099, 2020). "In this regard, the insulin receptor substrate 1, which represents a co-factors linked to tyrosine kinase receptors, seems to play a role in the pathogenesis of insulin resistance." (PMID 32681384, 2020). "Previously studies reported that genetic variants (rs2943641; rs2943650) in IRS1 were associated with insulin resistance, hyperinsulinemia, dyslipidemia, and T2DM." (PMID 32411229, 2020). "S. moranensis contains trans-resveratrol, which has been associated with increased phosphorylation of both Akt and IRS-1; this activation involves the reduction of both insulin resistance and gluconeogenic enzyme expression." (PMID 32194426, 2020). "We decided to focus on the two Irs genes because mutations in Irs1 are linked to type II diabetes and susceptibility to insulin resistance." (PMID 33330474, 2020). "In a type 2 diabetes mouse model (db/db), mTOR complex 1 (mTORC1) and S6K1 were chronically activated in the liver which was associated with insulin resistance and serine 1101 phosphorylation of IRS-1." (PMID 33303821, 2020). "Insulin resistance in obese mice through ER stress-mediated JNK pathway is induced by the phosphorylation of insulin receptor substrate 1 (IRS1), which impairs insulin action and causes insulin resistance." (PMID 32942585, 2020). "Insulin resistance is associated with increased serine phosphorylation of IRS-1 and inhibition of insulin-stimulated IRS-1 tyrosine phosphorylation and AKT activation." (PMID 31396538, 2019). "It is known that type-2 diabetes is an AD risk factor thus AD brains have markers of insulin resistance as Insulin Receptor Substrate-1 (IRS-1)." (PMID 31555123, 2019). "It is well known that TNF-α promotes insulin resistance by inhibiting IRS1 (insulin receptor substrate 1) and IL-1β causes apoptosis in β-pancreatic cells, thereby diminishing insulin production." (PMID 31430882, 2019). "Double phosphorylation of IRS-1 at S636/639, a key sight that has been implicated in insulin resistance, was dramatically reduced following treatment with higher concentrations of PA." (PMID 31426858, 2019).
Insulin resistance (continued). "It was initially thought that enhanced BCAA leads to activation of the mTOR/S6K1 kinase signaling pathway and phosphorylation of serine residues on IRS-1, which further cause insulin resistance." (PMID 31481892, 2019). "PTPN1 found from the network study is linked to the common network pathway and modulates insulin resistance through Jak-Stat, insulin receptor substrates (IRS1 and IRS2) and leptin signaling pathway." (PMID 30674322, 2019). "Although aberrant expression and phosphorylation of insulin receptor substrate 1 (IRS-1) contribute to insulin resistance, the underlying mechanism remains elusive." (PMID 31723029, 2019). "Some studies have shown that resistin affects glucose transport and causes insulin-stimulated insulin receptor substrate-1 (IRS-1) degradation leading to insulin resistance induction." (PMID 31236417, 2019). "Accumulating studies have demonstrated that aberrant IRS-1 expression including total protein down-regulation and abnormal phosphorylation play crucial roles in insulin resistance; however, the underlying mechanisms of IRS-1 dysregulation are still unclear." (PMID 31723029, 2019). "For example, in IRS-1-deficient mice, insulin resistance develops mainly due to decreased insulin-stimulated glucose metabolism in the muscle alone." (PMID 30717446, 2019). "In agreement with previous studies, the liver insulin resistance caused by lipid accumulation was associated with increased IRS-1 serine phosphorylation." (PMID 30030460, 2018). "Meta-analysis of several human studies indicated that IRS1 variants rs7578326 G-allele carriers and rs2943641 T-allele carriers had a lower risk of insulin resistance, T2D, and MetS." (PMID 30602666, 2018). "Women with the genotype of IRS1-rs2943641 TT exhibit reduction of insulin resistance and T2D risk when circulating vitamin D-25(OH)D is higher." (PMID 30602666, 2018). "IRS-1 has also been linked to ischemic stroke, possibly being an indicator of cardiovascular disease and increasing insulin resistance." (PMID 29856744, 2018). "As an indicator of insulin resistance, the insulin receptor substrate 1 (IRS-1) has been associated to ischemic stroke." (PMID 30305144, 2018). "The pathology of hyperinsulinemia-induced insulin resistance is associated with impaired Ser/Tyr phosphorylation of IRS-1 and IRS-2 that impairs their interactions with cytoplasmic domain of insulin receptors and deregulate the insulin signaling." (PMID 29786669, 2018). "Insulin receptor substrate 1 (Irs1) phosphorylation at serine 307 (which negatively controls tyrosine-phosphorylated Irs1 by insulin receptor associated with insuline resistance) was significantly increased in mesenteric arteries from db/db mice." (PMID 29440699, 2018). "Together, these findings suggested a novel mechanism in which up-regulation of miR-222 expression in obesity causes insulin resistance via hepatic IRS-1 repression." (PMID 29364977, 2018). "Abnormal signaling linked to insulin resistance has been already demonstrated in human AD brain including phosphorylated IRS1 and we have recently shown that metaflammasome proteins are present in AD brains compared to control brains." (PMID 29795582, 2018). "Increased serine phosphorylation of IRS-1 induces insulin resistance, suggestive of an association with AD pathogenesis." (PMID 29738527, 2018). "This activation can lead to phosphorylation of the insulin receptor substrate 1, leading to decreased insulin sensitivity which provides a potential link between higher protein intake and insulin resistance or T2D risk." (PMID 29329254, 2018). "PCOS has a profound effect on peripheral insulin resistance due to a reduction in insulin receptor substrate-1 (IRS-1) associated phosphatidylinositol (PI) 3-kinase activity in skeletal muscle." (PMID 30344510, 2018). "Several E3 ligases that target IRS-1 degradation have been implicated in triggering insulin resistance and related metabolic disorders." (PMID 29259227, 2017).
Insulin resistance (continued). "In parallel, and consistent with the expected insulin resistance which was associated with pIRS1-Ser636, a significant decrease in activating phosphorylation levels of IRS1 at Tyrosine-465 (pIRS1-Tyr465) was observed." (PMID 28386117, 2017). "TNF-α and IL-6 can cause insulin resistance by suppressing expression of the insulin receptor substrate −1 (IRS-1) and GLUT-4 though activation of NF-KB pathway." (PMID 28166749, 2017). "The IRS1 protein is critical for insulin response, and impairment of insulin signaling by IRS1 is linked to insulin resistance." (PMID 28117714, 2017). "Elevated levels of MAPK, NF-κB, and insulin receptor substrate 1 (IRS-1) along with reduced levels of Akt expression have been actively linked to the development of insulin resistance." (PMID 28814983, 2017). "Nevertheless, long-term consumption of HFD causes obesity and insulin resistance possibly by reducing the interaction between insulin and insulin receptor substrate-1 (IRS-1) via diacylglycerol signaling." (PMID 29176994, 2017). "We also examined the effects of DPP-4 inhibition in IRS-1-deficient mice fed an SL or SO diet as a model of insulin resistance." (PMID 26937254, 2016). "Here, we show that ‘selective insulin resistance' is caused by the differential expression of Irs1 and Irs2 in different zones of the liver." (PMID 27708333, 2016). "The SNP, rs2943650, near IRS1 has also been associated with a lower body fat percentage, increased triglycerides and insulin resistance, and lower HDL-cholesterol." (PMID 27312935, 2016). "The C allele at rs2943641 adjacent to IRS1 was identified as being associated with insulin resistance and hyperinsulinaemia in a European population." (PMID 27312935, 2016). "Increased Ser636 and reduced Tyr465 phosphorylation of IRS-1 has been linked to obesity-linked insulin resistance and type 2 diabetes." (PMID 27434075, 2016). "It has been well-established that inflammation is tightly associated with insulin resistance, and this action is proposed to be mediated through the impairment of insulin receptor substrate-1 by inflammatory molecules." (PMID 27220352, 2016). "Phosphorylation of these sites is associated with insulin resistance and also results in IRS-1 degradation." (PMID 25973388, 2015). "IRS-1 plays a pivotal point in the switch to insulin resistance, where serine phosphorylation of IRS-1 causes a conformational change in the IRS-1, preventing insulin induced tyrosine phosphorylation." (PMID 26400768, 2015). "Diabetic patients have a higher frequency of the IRS-1 Gly972Arg variant and this polymorphism is directly related to insulin resistance and subsequent hyperglycemia." (PMID 25859280, 2015). "Chronic inflammation is associated with obesity-induced insulin resistance, largely by inhibiting the insulin pathway at IRS-1." (PMID 26023930, 2015). "The genomic region ~500 kb upstream of IRS1 has been implicated in insulin resistance, type 2 diabetes, adverse lipid profile, and cardiovascular risk." (PMID 26090471, 2015). "In contrast, Tremblay indicated that amino acid-induced insulin resistance was linked to the S6K1-mediated phosphorylation of Ser1101 in IRS-1." (PMID 26084330, 2015). "In the first place, it has been reported that increased ROCK activity is associated with phosphorylation of insulin receptor substrate-1 (IRS-1) which thereby causes insulin resistance and blood glucose elevation." (PMID 26630989, 2015). "Given the essential function of IRS1 in insulin signaling and the association of IRS1 variants with T2D as well as fat% and BMI, this gene is likely to be involved in fat distribution, adipocyte biology and/or insulin resistance." (PMID 26363598, 2015). "Activation of the mTOR pathway results in phosphorylation of several residues of the IRS-1 protein, which can cause insulin resistance." (PMID 25973388, 2015).